INS (insulin)
Diseases named in the same sentence as INS in open-access papers (continued):
Sharing a sentence is not in itself a finding about the gene and the disease.
diabetes (continued). "The STZ-induced diabetes model (35 mg/kg) leads to a partial destruction of pancreatic beta cells and can serve as a model to evaluate the pancreatic effect of a substance that controls blood sugar on insulin secretion, cellular damage repair, and cellular regeneration." (PMID 41237113, 2025). "Furthermore, conventional therapies do not adequately target the underlying pathophysiological mechanisms of Type 2 Diabetes Mellitus (T2DM), particularly insulin resistance and β-cell dysfunction, leading to the progressive deterioration of β-cell function and subsequent disease progression." (PMID 39791180, 2025). "Diabetes mellitus (DM) is a long-term metabolic disease marked by reduced insulin action and/or absolute or relative insulin insufficiency." (PMID 40430475, 2025). "Notably, the withdrawal of insulin therapy was associated with specific clinical features, including shorter diabetes duration, lower baseline HbA1c levels and lower insulin requirement, highlighting the importance of an individualised treatment strategy tailored to patient characteristics." (PMID 40277315, 2025). "This protective effect was independent of established risk factors, including insulin therapy (odds ratio 2.84, 95% CI 2.41–3.35; p < 0.001), diabetes duration (odds ratio 1.03 per year, 95% CI 1.01–1.05; p = 0.001), and comorbidity burden (odds ratio 1.12 per point, 95% CI 1.06–1.18; p < 0.001)." (PMID 41048287, 2025). "Based on earlier studies, this approach selects people with type 1 diabetes while excluding virtually all those with type 2 diabetes, although there might be some severely ill type 2 diabetes patients whose poor renal function limits their diabetes medication to insulin only." (PMID 39755842, 2025). "Insulin-stimulated glucose disposal and forearm blood flow but not HbA1c or diabetes duration were positively associated with peak oxygen consumption during exercise indicating that insulin resistance has effects independent of hyperglycemia to reduce exercise capacity in these individuals." (PMID 39998445, 2025). "The Diabetes Control and Complications Trial (DCCT) indicates that sustained C-peptide concentrations are associated with lower rates of hypoglycemia, lower HbA1c levels, reduced insulin dose requirements and lower incidents of diabetes complications, such as retinopathy and nephropathy." (PMID 40607224, 2025). "Diabetes mellitus (DM) is a chronic metabolic disorder characterized by persistent hyperglycemia due to impaired insulin secretion, action, or both." (PMID 41128021, 2025). "India's lower cost of diabetes management compared to Pakistan and Bangladesh may be attributed to its robust domestic pharmaceutical industry, which produces affordable generic medications and insulin, significantly reducing treatment expenses." (PMID 40084317, 2025). "Therefore, targeting ER stress in β-cell has emerged as a potential therapeutic strategy in diabetes, as regulating insulin secretion from β-cells could potentially slow down the advancement of a pivotal component of the metabolic syndrome." (PMID 40260275, 2025). "Diabetes mellitus (DM) is a complex and heterogeneous group of metabolic disorders characterized by chronic hyperglycemia resulting from defects in insulin secretion, insulin action, or both." (PMID 40869934, 2025). "Furthermore, differences in preoperative insulin treatment between diabetes subgroups could reflect disease severity and may act as a potential confounder, although no participants received insulin postsurgery." (PMID 41409453, 2025). "Continuous Glucose Monitoring (CGM) devices represent technological advancements in diabetes management, as they offer a less intrusive method to measure glucose levels and, therefore, help improve the quality and style of life for type 2 diabetes patients, who are treated with insulin." (PMID 40801711, 2025).
diabetes (continued). "Furthermore, watercress extracts from the leaves, stems, and flowers appear to enhance insulin sensitivity and glycemic control in diabetes and show antiproliferative and pro-apoptotic effects in cancer models, with selective toxicity towards cancer cells and protective effects on normal cells." (PMID 40724606, 2025). "Additionally, exogenous insulin therapy to treat T1D drives “foreign” immune responses, emphasizing the need to study the development of “true” insulin autoimmunity during the pre-diabetes interval." (PMID 41259806, 2025). "Diabetes mellitus (DM) is a chronic metabolic disorder characterized by hyperglycemia resulting from defects in insulin secretion, action, or both." (PMID 40303529, 2025). "Notably, by year 3 (cohort 2) and year 5 (cohort 1), knowledge was reported as > 80% sustained in diabetes as a disease, risk factors, complications, differences between type 1 and type 2 diabetes, signs and symptoms of diabetes, nutrition therapy, exercise guidelines, and insulin therapy." (PMID 40126315, 2025). "In addition, researchers are actively developing glucose‐responsive “smart” insulins designed to activate only when blood glucose exceeds physiological thresholds, potentially revolutionizing diabetes treatment through the replacement of more physiological insulin." (PMID 40919135, 2025). "Disruptions in insulin signaling that regulate the GSK-3β pathway in diabetes, combined with hyperglycemia, may trigger tau phosphorylation and subsequent cleavage, which increases the risk of cognitive disorders, such as Alzheimer’s disease, in diabetic patients." (PMID 40909136, 2025). "Type 1 diabetes mellitus (T1DM), also known as juvenile-onset diabetes or insulin-dependent diabetes mellitus, develops as a result of an autoimmune response targeted against pancreatic insulin-producing β cells resulting in insulin deficiency and hyperglycemia." (PMID 40698658, 2025). "Diabetes mellitus (DM) is a chronic metabolic disorder characterized by persistent hyperglycemia resulting from impaired insulin production, secretion, or function." (PMID 40282188, 2025). "Diabetes mellitus (DM) is a complex metabolic disorder characterized by chronic hyperglycemia due to defects in insulin secretion and action." (PMID 41040769, 2025). "Therefore, it seemed rational to assess insulin injection practice among diabetes patients." (PMID 41306599, 2025). "This global survey reveals that economic barriers are the primary obstacle to diabetes technology access worldwide, with striking disparities between high-income and lower-income countries in the adoption of continuous glucose monitoring and insulin delivery systems." (PMID 40358737, 2025). "Thus, clinicians should be aware that people treated with insulin may experience higher diabetes distress." (PMID 39972441, 2025). "There is a lack of comprehensive pediatric pancreatic imaging repositories, which limits ultrasound (US)-based diagnosis and development of potential interventions, such as TUS stimulation for insulin release in diabetes mellitus (DM) therapy." (PMID 40969996, 2025). "Similarly, the National Health Insurance (NHI) in Japan ensures comprehensive diabetes care, funding billions of yen annually for insulin, glucose monitors, and advanced technology like CGMs, which has reduced diabetes complications and maintained low hospitalization rates." (PMID 41024507, 2025). "Similarly, physical activity improves insulin sensitivity and helps lower blood glucose levels, while regular glucose monitoring enables timely treatment adjustments, forming a foundation for effective diabetes management." (PMID 41214836, 2025). "Earlier age at menarche was associated with higher CRP, fasting insulin, and fasting glucose among US women aged median 44 years (IQR, 33-62) after adjusting for age, race/ethnicity, education, parity, menopause status, family history of diabetes, smoking status, physical activity, alcohol, and BMI." (PMID 38912813, 2025).
diabetes (continued). "In addition, diabetes-related neurodegeneration may also affect cognitive function through a variety of pathways, including insulin resistance, mitochondrial dysfunction and tau protein abnormalities." (PMID 40761848, 2025). "T2DM accounts for 90–95% of diabetes cases, typically developing later in life due to reduced insulin sensitivity in muscle, liver, and adipose tissue, and is often accompanied by a higher proinsulin-to-insulin ratio and impaired response to non–glucose stimuli." (PMID 40299501, 2025). "Diabetes mellitus (DM) is a heterogeneous metabolic disorder characterized by chronic hyperglycemia due to impaired insulin secretion, insulin resistance, or both." (PMID 41595838, 2025). "Similarly, following the DSEP training in evaluating confidence, participants reported that overall confidence and ability to help patients with diabetes in areas such as glucose monitoring and finger-sticks, insulin use, and diabetic foot exams were significantly improved and sustained (p < 0.001)." (PMID 40126315, 2025). "However, the mediation effects of TG or these insulin measurements were not significant in the associations of total SCFAs and propionate with diabetes risk." (PMID 40078932, 2025). "Diabetes mellitus (DM) is a chronic metabolic disorder characterized by persistent hyperglycemia due to inadequate insulin production or impaired insulin function." (PMID 40218965, 2025). "Pronounced disparities persist between low- and high-income countries in diabetes awareness, prevention, diagnosis, and treatment, driven significantly by inequitable access to and underutilization of modern management technologies, such as insulin delivery systems and continuous glucose monitoring." (PMID 40735640, 2025). "Thus, zinc insufficiency in people with diabetes might not only exacerbate inflammation and insulin dysfunction but could also diminish BDNF-mediated neural protection." (PMID 41142318, 2025). "Diabetes mellitus (DM) is a group of metabolic disorders characterized by high blood sugar (glucose) levels, a situation that arises due to defective insulin secretion, action, or both." (PMID 41476071, 2025). "Hence, if unexpected hyperglycaemia occurs and infusion set or pump failure is suspected, people with diabetes are advised to promptly check ketone and glucose levels, followed by correction doses via subcutaneous insulin injection and change of their infusion set as per sick day rules." (PMID 41354385, 2025). "Indeed, in a setting where optimal diabetes management and access to insulin are challenging, residual beta cell function may increase the risk of exposure to prolonged chronic hyperglycemia without acute decompensation (DKA)." (PMID 40458319, 2025). "Furthermore, it enhances insulin sensitivity and promotes glucose uptake by skeletal muscle cells, which can help in managing body weight, particularly beneficial for individuals with Type 1 diabetes mellitus (T1DM) and T2DM." (PMID 41030325, 2025). "Use of diabetes medication at onset of type 2 diabetes also showed regional variability, with the percentage of patients treated with oral glucose-lowering drugs ranging from 36.1% in EU to 69.8% in SA, while the percentage of patients treated with insulin ranged from 16.1% in NA to 55.4% in AS/AF." (PMID 39503771, 2025). "Additionally, elderly patients with DM2 with nursing home residency may have a longer diabetes duration, therefore impaired insulin secretion." (PMID 39964188, 2025). "However, a statement from the American Diabetes Association recommends reductions in basal insulin doses without specifying a cutoff point for how much the insulin dose can be reduced." (PMID 38954647, 2025). "Therefore, PARN serves as a crucial regulator of β-cell secretory capacity, and targeting the PARN–PTBP1–mRNA axis may offer novel therapeutic avenues for improving insulin secretion in diabetes." (PMID 40732992, 2025).
diabetes (continued). "MiRNAs regulate essential genes and signaling pathways involved in cellular processes such as insulin secretion, insulin sensitivity, pancreatic beta-cell function, glucose metabolism/homeostasis, platelet reactivity, and inflammation, all of which become dysregulated in diabetes." (PMID 41282296, 2025). "Aligned with efforts to integrate environmental sustainability, a recent HTA conducted in Italy by the ALTEMS Advisory research group estimated that introducing a new diabetes technology enabling weekly instead of daily insulin injections could reduce CO2 emissions by 865 tons over five years." (PMID 41332366, 2025). "Thus, more work is needed to understand how nEV insulin signaling biomarkers may relate to aging and diabetes‐related changes in the blood brain barrier and the transport of insulin from the periphery to the brain." (PMID 39421964, 2025). "Dysregulated mitotic checkpoint regulators may lead to abnormal insulin signaling in diabetes." (PMID 40260118, 2025). "Diabetes mellitus (DM) is a severe metabolic disorder characterized by an increase in blood glucose level due to insufficient insulin production or failure of insulin action on targeted tissues or both." (PMID 40687580, 2025). "Diabetes Mellitus (DM) is a chronic, serious metabolic disorder characterised by persistent hyperglycaemia resulting from impaired insulin secretion, insulin action, or both." (PMID 41375832, 2025). "Importantly, the inverse association observed in non-obese and non-diabetic individuals suggests that reduced muscle strength may represent an early subclinical marker of insulin-related metabolic dysfunction, preceding overt diabetes or metabolic syndrome." (PMID 41464556, 2025). "Moreover, intentional insulin omission for weight reduction is a unique diabetes-related DEB." (PMID 40163174, 2025). "When endogenous insulin production is insufficient to compensate for increasing insulin resistance, serum glucose levels go up leading to a pre-diabetic state (fasting glucose levels of 100–125 mg/dL and A1C 5.7–6.4%) and consequently to diabetes (fasting glucose levels ≥126 mg/dL and A1C ≥ 6.5%)." (PMID 40901288, 2025). "In conclusion, the future of natural polymer-based insulin delivery systems is incredibly promising, with advances in stimuli-responsive polymers, nanoparticle carriers, scalable manufacturing, and personalized medicine paving the way for more effective and patient-friendly diabetes treatments." (PMID 40352348, 2025). "In addition, the supraphysiological glucose concentrations commonly used in vitro, as well as those observed in diabetic mouse plasma, may not represent the glycemic profiles of most individuals with diabetes undergoing insulin therapy." (PMID 41124286, 2025). "Diabetes mellitus (DM) is a metabolic disease that leads to hyperglycemia due to defects in insulin secretion and/or function." (PMID 39911635, 2025). "Finally, we observed that for PDAC patients with NOD, the percentage receiving treatment for diabetes, including both oral antidiabetic medications and insulin, increased from 40.5% preoperatively to 77.8% at discharge from the hospital, with insulin use increase from 21.6% to 41.3%." (PMID 40557340, 2025). "Diabetes mellitus is a long-term metabolic disorder that is primarily divided into three distinct categories: type 1 (manifested by inadequate insulin secretion), type 2 (prompted by resistance to insulin), as well as gestational diabetes (characterized by maternal peripheral insulin resistance)." (PMID 41333774, 2025). "Comprehensive education programs on insulin usage should empower individuals with DM and serve as vital components of effective diabetes management." (PMID 40226177, 2025). "Diabetes mellitus (DM) is a chronic metabolic disorder characterized by persistently elevated blood sugar levels due to insufficient insulin secretion and reduced insulin sensitivity." (PMID 39949440, 2025).
diabetes (continued). "Type 2 diabetes mellitus (T2DM), one of the types of DM, affects the majority of diabetic patients around the world, and it arises from impaired insulin secretion and utilization by the body." (PMID 40735405, 2025). "Diabetes mellitus (DM) is a chronic metabolic disorder marked by sustained hyperglycemia resulting from insufficient insulin secretion or impaired insulin utilization." (PMID 40808704, 2025). "Furthermore, consumption sugar alcohol has been shown to cause minimal to no increase in blood sugar levels or insulin secretion, making them a recommended option for individuals with diabetes." (PMID 40724359, 2025). "Insulin overbasalization not only represents a deviation from recommended practices but may also indicate broader issues in diabetes management, including clinical inertia, the failure to escalate treatment in a timely fashion when therapeutic goals are not met." (PMID 40909026, 2025). "This study aimed to evaluate whether CGM use in combination with anti‐diabetes medications is associated with changes in A1c among people with type 2 diabetes not using insulin." (PMID 40851538, 2025). "Dogs and cats with naturally occurring DM provide valuable translational models that aid veterinary drug development and human diabetes research, particularly in areas such as insulin pharmacokinetics, formulation design, and behavioral adherence to therapy." (PMID 41012437, 2025). "Diabetes mellitus (DM) is a chronic metabolic disease primarily characterized by hyperglycemia, which results from either defective insulin secretion or insulin resistance." (PMID 40076247, 2025). "Notably, insulin is widely prescribed in inpatient settings for diabetes treatment." (PMID 40150028, 2025). "Diabetes mellitus (DM) is a group of metabolic diseases characterized by hyperglycemia due defects in insulin secretion, insulin action, or both." (PMID 41295239, 2025). "Therapeutic strategies targeting IRS stability (e.g., kinase inhibitors), Foxo1 activity, or mitochondrial biogenesis may restore metabolic plasticity and mitigate disease progression, highlighting the interplay between insulin signaling fidelity and cardiac resilience in diabetes." (PMID 40747301, 2025). "Importantly, lifestyle intervention in the Diabetes Prevention Program (DPP) study was associated higher cardiac NT-proBNP levels with improved insulin sensitivity, independent of weight status." (PMID 39097697, 2024). "A collection of metabolic conditions known as diabetes mellitus (DM) is characterized by high blood glucose levels due to decreased insulin circulation in the body, insulin resistance, or increased synthesis of counter-regulatory hormones." (PMID 38882975, 2024). "This review delves into the current state of nanomedicine for insulin delivery, examining various types of nanocarriers and their mechanisms of action, and discussing the challenges and future directions in developing safe and effective nanomedicine-based therapies for diabetes management." (PMID 39065795, 2024). "Diabetes mellitus (DM) is a multifactorial metabolic disorder characterized by dysregulation of glucose metabolism, originating from inadequate insulin secretion by pancreatic beta cells and/or impaired insulin sensitivity, leading to persistent hyperglycemia and several important complications." (PMID 38672103, 2024). "Therefore, it is promising that enhancement of insulin action in the skeletal muscle, especially suppression of FoxO, is effective in preventing sarcopenia in diabetes and that myokines from the skeletal muscle can be identified and targeted for prevention and treatment of aging-related diseases." (PMID 39513056, 2024). "More in-depth research revealed that insulin reduces 12α-hydroxylated bile acids, cholesterol absorption, and plasma cholesterol levels by inhibiting FoxO1, which may contribute to the high risk of CVD in diabetes." (PMID 38406276, 2024).